GCG (glucagon)
Diseases named in the same sentence as GCG in open-access papers (continued):
Sharing a sentence is not in itself a finding about the gene and the disease.
Hyperglycemia (continued). "Both mouse models suggest loss of insulin-mediated intra-islet suppression of glucagon production, and with this in mind, we have made a preliminary exploration of leptin treatment in Akita mice, intended to suppress the hyperglycemia with hyperglucagonemia." (PMID 28702245, 2016). "Although suppression of glucagon action is likely to attenuate the consequences of insulin deficiency, its primary role in the hyperglycemia is uncertain." (PMID 27092792, 2016). "Here we show that near-total β-cell loss triggers severe hyperglycemia and all the metabolic features of type 1 diabetes (cachexia, glucose intolerance, and death) in mice with constitutive or induced glucagon signaling deficiency." (PMID 27092792, 2016). "Because of the reduction of insulin:glucagon molar ratio, basal endogenous glucose concentration will be higher, causing fasting hyperglycemia and contributing to excessive postprandial glucose rise." (PMID 25961284, 2015). "By augmenting glucose-dependent insulin secretion and inhibiting glucagon secretion these medications also target the underlying pathophysiology found in patients with stress-induced hyperglycemia." (PMID 28702223, 2015). "Chronic hyperglycaemia was associated with a ~20-fold increase in cells positive for both insulin and glucagon (ins+/glu+ cells) in islets from 4-week-diabetic βV59M mice." (PMID 25145789, 2014). "Recent studies have indeed demonstrated that the elimination of glucagon action by whole-body deletion of its receptors prevents hyperglycemia in mice with STZ-induced insulin deficiency." (PMID 23620811, 2013). "Impaired muscle glucose uptake is the main cause of postprandial hyperglycemia whereas overproduction of glucose by the liver and glucagon dysregulation are the main causes of fasting hyperglycemia." (PMID 24151620, 2013). "Physiologically, GABA acts synergistically with insulin to inhibit the secretion of glucagon by the pancreatic α-cells, and reverse insulin-deficiency-related hyperglycemia in mice." (PMID 21966503, 2011). "L-menthol’s antispasmodic properties make it a promising alternative for patients who cannot tolerate conventional agents, such as hyoscine butylbromide or glucagon, which are associated with systemic side effects, including dry mouth, urinary retention, and hyperglycemia." (PMID 40566063, 2025). "In addition, the drug has been shown to reduce fasting blood glucose by stimulating insulin secretion and lowering glucagon secretion when blood glucose is high, which is crucial for preventing complications associated with hyperglycemia." (PMID 41364787, 2025). "In addition, it delays gastric emptying, causing a decrease in postprandial hyperglycemia; decreases appetite; and increases the feeling of satiety, which leads to a reduction in body weight and reduces plasma glucagon." (PMID 41012462, 2025). "Moreover, GLUT-2-deficient mice exhibited glucagon hyperglycemia that was subsequently normalized through nerve blockade, demonstrating the involvement of GLUT-2 in regulatory linkages associated with nerve signaling." (PMID 38333863, 2024). "Given the known association of glucagon with hyperglycemia, glucagon agonism may appear counterintuitive in treating T2DM and obesity." (PMID 39061960, 2024). "HbA1c was most strongly, and inversely, associated with glucagon lowering during hyperglycemia." (PMID 37708362, 2024). "Diabetic ketoacidosis (DKA) is a life-threatening medical emergency and is a direct result of a lack of insulin or insulin resistance, which leads to increased levels of counterregulatory hormones, such as glucagon, cortisol, and catecholamines, thereby causing hyperglycemia." (PMID 39360087, 2024). "Arginine is essential for producing arginine-vasopressin, which may contribute to symptoms such as hypertension and hyperglycemia associated with glucagon production." (PMID 39707182, 2024).
Hyperglycemia (continued). "Propionate may cause glycogenolysis, insulin resistance, and hyperglycemia by increasing plasma levels of glucagon, insulin counter-regulatory hormones, and fatty acid-binding protein 4 (FABP4) in both mice and humans." (PMID 37432305, 2023). "This caused wrongful glucagon administration and subsequent hyperglycemia." (PMID 36755913, 2023). "In addition, we elucidated the molecular mechanism underlying GnIH-mediated hyperglycemia and dyslipidemia: GnIH disturbed the synthesis of insulin and glucagon in the pancreas as well as fatty acid biosynthesis and fatty acid oxidation in eWAT." (PMID 35897643, 2022). "It is also important to note that the state of hyperglycaemia induced by acute glucagon administration may increase cardiometabolic disease risk." (PMID 36123404, 2022). "However, glucagon is the key counter-regulatory hormone of insulin, and the development of GCGR agonists has been hampered by a glucose-centric perspective on glucagon’s ability to cause hyperglycemia at pharmacological levels." (PMID 36356832, 2022). "We hypothesized that the significant resistance against STZ-induced hyperglycemia in the OMPlox/lox;GCGcre/w mice was caused by altered glucagon secretion from OMP-deleted α-cells." (PMID 36104518, 2022). "Conversely, impaired suppression of glucagon is uniquely associated with the portal insulin deficiency that occurs with exogenous insulin delivery in T1D, leading to hyperglycemia due to paradoxical hyperglucagonemia at other times, such as during overnight fasting and after meals." (PMID 36992764, 2022). "For instance, anticholinergics, such as atropine and hyoscine-N-butylbromide, can result in decreased saliva secretion, blurred vision, glaucoma, palpitations, and allergic reactions, and glucagon has been reported to be associated hyperglycemia, reactive hypoglycemia, and allergic reactions." (PMID 34347808, 2021). "For GCG analogs, prolonged cAMP signaling was seen with agonists displaying reduced β-arrestin-2 recruitment, but this did not translate to increases in downstream responses linked to hyperglycemia in the models tested." (PMID 33268378, 2021). "This delay may be caused by the fish being stimulated to secrete glucagon and somatostatin hormones under the stress of hyperglycemia, thereby inhibiting the secretion of insulin and delaying the change in insulin in response to plasma glucose." (PMID 33178047, 2020). "A simple feedback model cannot adequately capture the two effects of hyperglycemia underlying the paradoxical increase of glucagon secretion, because it is centered on negative control loops between glycemia and two pancreatic hormones, insulin and glucagon." (PMID 32132928, 2020). "Notably, the role of other pathways, that are implicated in the development of hyperglycaemia, including pancreatic secretion of insulin, glucagon, lipolysis, glucose uptake, renal absorption, neurotransmitter signaling, etc cannot be ruled out." (PMID 33088930, 2020). "In addition, an increase in glucagon secretion in hyperglycemia is associated with an increased activity of protein kinase C delta (PKC-δ)." (PMID 32774668, 2020). "While our data demonstrate that cervical VNS can cause hyperglycemia through inhibition of glucose‐induced insulin release, mechanisms other than inhibition of insulin or stimulation of glucagon release likely contributed to the elevated fasted blood glucose levels with VNS." (PMID 30569658, 2018). "In conclusion, this is the first report of a PAX4 gene KO model in rabbits, including characteristics of growth retardation, persistent hyperglycemia, decreased number of insulin-producing β cells, increased number of glucagon-producing α cells and typical DM associated phenotypes." (PMID 29950431, 2018). "Moreover, mice that developed hyperglycaemia showed glucagon positivity but a loss of insulin positivity in a number of islets, indicating destruction of the insulin-producing beta cells." (PMID 29151123, 2018).
Hyperglycemia (continued). "Pre-clinical studies have confirmed that these analogues can reduce body weight in obese mice models as well as improve blood glucose with chronic administration, even if acutely the glucagon component may cause a transient hyperglycaemia." (PMID 29412829, 2018). "On the other hand, the hyperglucagonemia following chemotherapy, which may be related to decreased glucagon degradation associated with impaired renal function, contributed to the formation of the hyperglycemia in rats." (PMID 29338697, 2018). "Therefore, to safely harness the attractive catabolic and thermogenic effects of glucagon for treating metabolic disease, a counter-balancing therapy that selectively opposes the risk for glucagon-induced hyperglycaemia is required." (PMID 28733905, 2017). "Loss of insulin-mediated intra-islet suppression of glucagon production may be a contributor to hyperglycemia in Akita mice, and leptin treatment appears beneficial in such a circumstance." (PMID 28702245, 2016). "Hyperglucagonemia, which is believed to derive mainly from a loss of insulin-mediated intra-islet suppression of glucagon production, is increasingly recognized as an important cause of hyperglycemia, and we have reported hyperglucagonemia as a phenotypic feature in MIDY patients." (PMID 28702245, 2016). "Hyperglycemia as a result of reduced insulin production caused by increased glucagon synthesis (postagression metabolism) might be one explanation for the increased glucose levels." (PMID 27978832, 2016). "It has been reported that the manipulation of glucagon by receptor agonists, such as glucagon-like peptide-1 (GLP-1), or by dipeptidyl peptidase-4 (DPP-4) inhibitors can decrease glucagon levels and eventually reduce the degree of hyperglycemia and its associated risks." (PMID 27092078, 2016). "Moreover, several studies demonstrated that such animal models do not develop hyperglycaemia after beta cell destruction by streptozotocin (STZ) treatment, suggesting that glucagon plays an indispensable role in hyperglycaemia caused by beta cell destruction." (PMID 27053237, 2016). "Insulin deficiency, elevated glucagon release, and progressive loss of amylin are the major pancreatic defects; derangements in incretins and gut hormones may contribute to post-prandial hyperglycemia, satiety issues, and problems with gastric emptying." (PMID 27398228, 2016). "Interestingly, the effects of hyperglycemia on β-cell dedifferentiation, loss of insulin content and glucagon expression can be reversed by tight control of blood glucose." (PMID 25982967, 2015). "Herdt and Emery also add that a glucose injection may cause a reduction in glucagon plasma since its secretion decreases in response to hyperglycaemia." (PMID 26500763, 2015). "Moreover, the combination of glucagon with GLP-1 actions could improve WL while protecting against the risk of hyperglycaemia." (PMID 38302593, 2025). "However, chronic hyperglycemia is associated with profound alterations in glucagon secretion, which may account for the differences." (PMID 39599691, 2024). "However, the potential loss of a glucagon-mediated potentiating effect on remaining β-cells due to a reduction in basal glucagon release may be less critical than a beneficial reduction in hyperglycemia induced by suppression of α-cell glucagon secretion." (PMID 37152965, 2023). "Synthesizing the limited data available, glucagon secretion may be dysregulated in TS, but there is insufficient evidence to say that hyperglucagonemia plays a predominant role in the heightened risk for hyperglycemia in TS." (PMID 36875465, 2023). "Therefore, elevated post-prandial glucagon levels might represent a potential underlying mechanism involved in post-prandial hyperglycemia and progression to DM in CD." (PMID 35563608, 2022). "In animal studies, diets rich in Se may promote the release of glucagon causing s hyperglycemia." (PMID 32774440, 2020).
Hyperglycemia (continued). "Hyperglycemia-induced oxidative stress causes pancreatic β-cell dysfunction due to pro-inflammatory cytokines which induce the release of insulin counter-regulatory hormones (glucagon, cortisol and growth hormone) leading to increased hepatic gluconeogenesis and hyperglycemia." (PMID 27073901, 2016). "The beneficial effects of FOS supplementation (decrease in hyperglycemia, improvement of insulin sensitivity) in animal models of obesity are reported to be partly linked to an increased expression of proglucagon and production of glucagon-like peptide-1 by endocrine L-cells present in the colon." (PMID 21707971, 2011). "This hypoinsulinemia, along with insulin resistance and excessive catabolism due to counter‐regulatory hormones (cortisol, catecholamines, growth hormone, and glucagon), leads to hyperglycemia." (PMID 40931439, 2025). "Studies in αTC1-6 cells — a model of α cells — show that, under chronic hyperglycemia, glucagon granules misroute from degradative LAMP2+ lysosomes to LAMP1+ secretory lysosomes, contributing to hypersecretion." (PMID 41026524, 2025). "Studies have shown that severe physiological stress (e.g., sepsis) can induce metabolic abnormalities (e.g., elevated cortisol, glucagon, and catecholamines), leading to stress-induced hyperglycemia." (PMID 40314033, 2025). "Postprandial hyperglycemia depends on several factors, such as quantity and composition of food, content of carbohydrate as well as production of insulin and inhibition of glucagon secretion." (PMID 39859258, 2025). "Both of these factors are suggested to independently influence sympathetic activity and blood pressure, and increases in resting sympathetic activity can lead to increases in circulating catecholamines and glucagon, further exacerbating hyperglycemia." (PMID 40104147, 2025). "Inappropriate glucagon secretion, especially a failure to suppress glucagon during hyperglycaemia, antagonises insulin and can blunt the early insulin response and dampen pulsatility." (PMID 41226286, 2025). "By enhancing glucose-dependent insulin secretion and suppressing glucagon release, these agents reduce chronic hyperglycemia-induced oxidative stress and AGE accumulation, thereby attenuating glomerular basement membrane thickening and albuminuria." (PMID 40534883, 2025). "Among these mechanisms, elevated hepatic gluconeogenesis (mediated by glucagon activity) contributes more significantly to hyperglycemia than impaired glucose utilization." (PMID 41614828, 2025). "Others believe that steroids promote β-cell apoptosis and increase glucagon secretion from α-cells, leading to persistent hyperglycaemia." (PMID 41567924, 2025). "Compounding this, α-cell dysfunction leads to inappropriate elevation of glucagon secretion during hyperglycaemia, and over time, individuals also develop a blunted glucagon response to hyperglycaemia." (PMID 40718205, 2025). "Offspring had a significantly higher body weight, especially the male offspring (1.2‐fold), which also exhibited hyperglycemia, hyperlipidemia, insulin resistance, and elevated circulating glucagon and free fatty acids." (PMID 39825581, 2025). "Hyperglycemia in T2DM results from reduced glucose utilization due to non-autoimmune insulin deficiency and the excessive production of glucagon." (PMID 41614828, 2025). "Infusion of GIP during a mixed meal further increases circulating levels of glucagon in people with T2D, and this coincides with a greater glucose excursion and thus postprandial hyperglycemia." (PMID 40024571, 2025). "Long-acting agents such as semaglutide, liraglutide, dulaglutide, and exenatide (extended-release) increase insulin secretion and suppress glucagon levels to modulate post-prandial hyperglycemia." (PMID 41393547, 2025). "Insulin resistance results in elevated hepatic glucagon levels and intensified hepatic glucagon responsiveness, prompting the liver to produce excessive glucose, thereby contributing to the onset of hyperglycemia in T2D." (PMID 40647906, 2025).
Hyperglycemia (continued). "Previous studies showed that prolonged hyperglycemia sustains mTORC1 activity in α cells, leading to elevated glucagon secretion." (PMID 41026524, 2025). "In T1DM, the lack of endogenous insulin eliminates its inhibitory effect on pancreatic α-cells, leading to increased glucagon secretion even during hyperglycemia." (PMID 40822953, 2025). "GLP-1 receptor agonists delay gastric emptying, suppress glucagon secretion, and can reduce postprandial hyperglycemia, offering the potential to further optimize glucose control beyond what insulin-only closed-loop systems can achieve." (PMID 40231429, 2025). "As a consequence, the lipid-lowering effects of glucagon are blunted, promoting hepatic triglyceride accumulation and persistent hyperglycemia." (PMID 40822953, 2025). "Insulin administration is effective for suppressing hyperglycemia and glucagon secretion, lipolysis, and ketogenesis, and it is recommended to start continuous infusion at 0.1 units/kg/hour." (PMID 40546498, 2025). "In children/adolescents with T1D, postprandial plasma glucagon levels have been reported to increase progressively over time following diagnosis and correlate positively with postprandial hyperglycemia and the decline in β-cell function." (PMID 39998445, 2025). "Accordingly, a glucagon-dependent hyperglycaemia is described as promoting cancer progression and angiogenesis under the activation of HIF1α pathways, which is the main controller of glycolysis." (PMID 40649254, 2025). "Subsequent studies revealed that co-infusion of GLP-1 with GCG can mitigate the GCG-induced hyperglycaemia, while preserving GCG’s metabolic benefits, providing a strong rationale for the development of GLP1/GCG co-agonists as obesity treatments." (PMID 40741227, 2025). "GLP-1RAs achieve glycemic control through mechanisms such as boosting insulin secretion induced by hyperglycemia, decreasing glucagon secretion during hyperglycemia, slowing gastric emptying, and preventing significant increases in postprandial glucose." (PMID 39184671, 2024). "Their known mechanisms of action include slowing gastric transit, promoting hyperglycemia-induced insulin secretion, and suppressing glucagon secretion in hyperglycemia." (PMID 39238749, 2024). "Taken together, the KcnK16 L114P mouse model shows disrupted glucagon and insulin secretion leading to fasting hyperglycemia and glucose intolerance, which provides confirmation that TALK-1 gain-of-function mutations likely cause MODY." (PMID 38700926, 2024). "Elevated levels of serum glucose can trigger INS and ADPN release or decrease glucagon production to alleviate stress from hyperglycemia and maintain the glucose balance." (PMID 38668364, 2024). "Given that glucagon levels rise within an hour after ZT-01 dosing, we also assessed the potential for ZT-01 administration to exacerbate hyperglycemia when glucose levels are stimulated, such as after feeding (which we simulated using an OGTT)." (PMID 38510652, 2024). "They focused on educating the patient in the area of practical skills, i.e., measuring glucose levels and administering insulin or glucagon, as well as dealing with hypo and hyperglycemia." (PMID 38486206, 2024). "As previous research has shown that nickel can induce hyperglycemia through increased hepatic glycogenolysis, heightened pancreatic glucagon release, reduced peripheral utilization of glucose or gluconeogenesis." (PMID 39564359, 2024). "Targeting excessive postprandial glucagon secretion represents a potential strategy to mitigate hyperglycemia in individuals with T1D." (PMID 39149119, 2024). "Conversely, high plasma levels of glucose inhibit glucagon secretion, which decreases hepatic glucose production, reduces hyperglycaemia and decreases the inhibition of glucagon secretion." (PMID 38579751, 2024).